PKD2 (polycystin 2, transient receptor potential cation channel)
Diseases named in the same sentence as PKD2 in open-access papers (continued):
Sharing a sentence is not in itself a finding about the gene and the disease.
breast carcinoma (continued). "Suppressing either PKD2 or PKD3 was able to reduce breast cancer cell proliferation and metastasis." (PMID 30652415, 2019). "To date, there are no reports linking PKD2 to focal adhesion (FA) function, except one study indirectly showing that PKD (as detected with a pan-antibody that picks up PKD1 and PKD2), as well as cortactin and FA-localized paxillin can be isolated from invadopodia of breast cancer cells." (PMID 28842658, 2017). "Inhibition of PKD2 activation could significantly inhibit the expression of P-gp and decrease multiple drug resistance (MDR) in human breast cancer cells, indicating that PKD2 may be an important target for tumor biotherapy and MDR reversal." (PMID 26919108, 2016). "In breast cancer cells, depletion of PKD1 stimulated migration in MCF-7 cells; however, the effect was higher when PKD2 was silenced." (PMID 37293129, 2023). "Consistently, both PKD2 and PKD3 were preferentially expressed in most of the breast cancer tissues (13 out of the 16 breast cancer tissues)." (PMID 30652415, 2019). "Compared to PKD1, PKD2 and PKD3 were expressed at higher levels in the invasive breast cancer cell lines through analyzing the gene expression data from Cancer Cell Line Encyclopedia project and NCI60 Cell Line project." (PMID 30652415, 2019). "In this study, we found PKD2 and PKD3 were the two major isoforms of PKD overexpressed in breast cancer." (PMID 30652415, 2019). "In order to determine which of these two PKD isoforms are responsible for PIP5K1C phosphorylation in breast cancer cells, we compared MCF-7 cells, which express all three PKD isoforms, to MDA-MB-231 cells, which only express PKD2 and PKD3." (PMID 30555634, 2018). "At this point it is unclear if in invasive breast cancer cells and tissue VASP phosphorylation at both sites is exclusively regulated PKD2, since both also can be targeted by AMPK, a metabolic gauge associated with tumorigenesis." (PMID 26336132, 2015). "Among the 69 ciliary-associated genes analyzed, seven genes showed a statistically significant decrease in expression in breast cancers (log fold change: DYNC2H1 = -0.66; IFT46 = -1.07; PKD2 = -1.67; NPHP3 = -1.10; BBS2 = -1.51; BBS4 = -0.78; TTC8 = -1.46)." (PMID 24987519, 2014). "Of note, the other two PKD isoforms, PKD2 and PKD3, were upregulated in all breast cancer cell lines independently of their invasive potential." (PMID 23971832, 2013). "Both PKD2 and PKD3 were preferentially expressed in breast cancer compared to PKD1." (PMID 30652415, 2019). "Unlike PKD1 and PKD3, the expression pattern of PKD2 remains relatively unchanged during breast cancer progression." (PMID 26848698, 2016). "In this context, the higher PKD3 levels during breast cancer progression compared with PKD2 and the near absence of PKD1 expression suggest that PKD3 activity may be independent of the expression of the other isoforms, which would support the idea of an autonomously functioning oncogene." (PMID 37293129, 2023). "In contrast, PKD1 expression is absent and PKD2 and PKD3 expression levels are elevated in breast cancer." (PMID 34249722, 2021). "In the current study, we found that PKD2 and PKD3 but not PKD1 were preferentially overexpressed in breast cancer and involved in regulating cell proliferation and metastasis." (PMID 30652415, 2019). "The differential expression pattern of PKD2 and PKD3 when compared to PKD1 in breast cancer suggests that the PKD family members do not exhibit the same functions in biological processes like EMT and cell migration." (PMID 26848698, 2016). "Similarly, PKD2 and PKD3, but not PKD1, were expressed in the highly metastatic breast cancer cell lines MDA-MB-231 and MDA-MB-468." (PMID 33807058, 2021).
breast carcinoma (continued). "For example, NRAS, a well‐characterized oncogene, was downregulated upon silencing PKD2 and silencing both PKD2 and PKD3, but not suppressed when silencing PKD3 in both MDA‐MB‐231 and MDA‐MB‐468 cells, which suggested differentially regulatory roles of PKD2 and PKD3 in breast cancer." (PMID 30652415, 2019).
renal failure (14 papers, 2008 to 2025). "In keeping with other reports, the PKD2 phenotype in this family was overall mild, and characterized by conserved kidney function, although 12 cases had some evidence of renal insufficiency." (PMID 24011172, 2013). "Finally, we establish a functional link between TMEM33 and acute kidney injury (AKI), while Pkd2-dependent cystogenesis is independent of TMEM33." (PMID 31048699, 2019).
liver cysts (13 papers, 2014 to 2026). "Among 42 patients with bilateral PKD caused by PKD1 and/or PKD2 mutations, 11 (26.2%) had combined hepatic cysts or polycystic liver." (PMID 31056860, 2019). "In ADPKD, while PKD1 and PKD2 mutations are known to cause both kidney and liver cysts, the presence of liver cysts without kidney involvement may indicate other genetic causes." (PMID 41411243, 2025).
prostate carcinoma (13 papers, 2010 to 2024). A carcinoma that arises from epithelial cells of the prostate gland. "For example, we have shown that depletion of PKD2 causes accumulation of cells in G2–M and delays the mitotic entry of prostate cancer cells." (PMID 33807058, 2021). "In prostate cancer, on the other hand, decreased invasion and expression of genes related to bone metastasis was observed upon PKD2/3 knockdown or CRT0066101 inhibition." (PMID 38323010, 2024). "As PKD3 and PKD2 are both Hsp90 clients (and our study), it is plausible that their shared activities in prostate cancer metastasis are co-regulated by Hsp90." (PMID 36672148, 2023). "PKD3 together with PKD2 promotes prostate cancer cell migration through the expression and activation of urokinase-type plasminogen activator (uPA) via the NF-κB pathway." (PMID 36672148, 2023). "Results from the migration assays showed that mast cell migration was mediated via various chemokines including SCF, CCL5 and CCL11 secreted by PKD2/3 expressed-prostate cancer cells." (PMID 36836690, 2023). "PKD3 together with PKD2 initiate prostate cancer cell migration by modulating urokinase-type plasminogen activator (uPA) expression and activation in a nuclear factor kappa B (NF-κB) and histone deacetylase 1 (HDAC1)-mediated manner." (PMID 36672148, 2023). "We found that ganetespib dose-dependently depleted the protein level of PKD3, PKD2, and Akt, which are important regulators of prostate cancer progression." (PMID 36672148, 2023). "PKD2/3 promotes prostate cancer angiogenesis through regulating mast cell recruitment and microvessel density in the tumor microenvironment." (PMID 35805075, 2022). "In prostate cancer cells, PKD2 played an antiapoptotic role in phorbol ester-induced apoptosis in androgen-sensitive prostate cancer cells through the ERK1/2 and NF-κB pathways." (PMID 33807058, 2021). "We then explored the effect of PKD2 or PKD3 on the activation of Erk1/2 or NF-κB signaling in response to PKDs agonist PMA in prostate cancer cells." (PMID 30841931, 2019). "In prostate cancer cells with overexpressed with PKD2 and PKD3, ELISA and RT-qPCR assay demonstrated that Erk specific inhibitor PD98059 (PD) antagonized the upregulation of SCF and CCL5 expression induced by PKD2 or PKD3 in DU145 cells." (PMID 30841931, 2019). "PKD2/3 contributed to MCs recruitment and tumor angiogenesis in the prostate cancer microenvironment." (PMID 30841931, 2019). "Collectively, these results indicated that PKD2/3-NF-κB and PKD2/3-Erk1/2 axes played an important role in prostate cancer cell." (PMID 30841931, 2019). "PKD2/3 silencing of prostate cancer cells markedly decreased MCs migration and tube formation of HUVEC cells." (PMID 30841931, 2019). "Taken together, these results indicate that AP-1 and NF-κB play a central role in the transactivation of scf, ccl5 and ccl11 induced by PKD2 or PKD3 in prostate cancer cells." (PMID 30841931, 2019). "Furthermore, mast cells when co-cultured with human prostate cancer cell lines that express PKD2/3 promoted prostate cancer migratory abilities, implicating a role of PKD2/3 in associating with mast cell infiltration in the prostate cancer." (PMID 36836690, 2023). "The phosphorylation of Ser536 by PKD3 as well as that of Ser276 by PKD2 are both critical for the transactivation of NF-κB and the expression of the urokinase-type plasminogen activator (uPA), which is in turn, indispensable for prostate cancer cell invasion." (PMID 36672148, 2023). "Since PKD2 has been identified as an Hsp90 client, we hypothesized that Hsp90 might promote prostate cancer cell migration via PKD3." (PMID 36672148, 2023). "In prostate cancer cells, PKD2/3 activation triggers the ERK1/2 and NF-κB signaling pathways." (PMID 35805075, 2022). "We then explored whether PKD2/3 of prostate cancer cells mediated HUVECs tube formation through upregulation of VEGF expression in mast cells." (PMID 30841931, 2019).
prostate carcinoma (continued). "Also, our finding showed that PKD2/3 of prostate cancer cells was involved in MCs recruitment and angiogenic factors expression in MCs leading to angiogenesis." (PMID 30841931, 2019). "Given that multiple autocrine or paracrine chemokines such as SCF, CCL5 and CCL11 mediated MCs migration and recruitment, so we verified whether PKD2 or PKD3 could regulate these chemokines expression in the prostate cancer cells." (PMID 30841931, 2019). "Both, PKD2 and PKD3 are necessary for the expression of genes associated with metastasis and invasion, such as urokinase-type plasminogen activator (uPA) and MMP-9 in prostate cancer cells." (PMID 26848698, 2016). "Prostate cancer cell migration and invasion are dependent on both PKD2 and PKD3." (PMID 26848698, 2016). "PKD1 and PKD2 play anti-apoptotic and pro-survival roles in response to the apoptotic agent PMA, a phorbol ester, in LNCaP prostate cancer cells." (PMID 35805075, 2022). "These PKD2- and PKD3-mediated signaling events coordinated to promote prostate cancer cell invasion." (PMID 33807058, 2021). "We previously demonstrated that PKD2 and PKD3 interact with IKKβ, and mediate the pIκB kinase (pIKK)-pIκB-IκB degradation cascade in prostate cancer cells." (PMID 30841931, 2019). "Depletion of PKD2 and PKD3 in prostate cancer cells significantly decreased binding of p65, c-Jun and c-Fos to the scf, ccl5, and ccl11 promoter." (PMID 30841931, 2019). "Later in 2012, Zhipeng Zou published an article and demonstrated that PKD2 and PKD3 coordinated to promote prostate cancer cell invasion through NF-κB and HDAC1-mediated expression and activation of uPA21." (PMID 30718593, 2019). "Recent work in prostate cancer identified that PKD2 or PKD3 knockdown results in decreased expression and secretion of pro-inflammatory chemokines SCF, CCL5 and CCL11 in two prostate cancer cell lines, with the proteins contributing to the chemotactic migration of mast cells in vitro." (PMID 38323010, 2024). "Nevertheless, these findings show a critical requirement for both Hsp90 and PKDs (and related kinases) for prostate cancer cell migration, which is consistent with previous data showing roles for PKD3, PKD2, and Hsp90 in prostate cell migration and tumor metastasis." (PMID 36672148, 2023). "Both PKD2 and PKD3 have a cooperative role in prostate cancer cell migration and invasion." (PMID 35805075, 2022). "Additionally, both PKD2 and PKD3 have been shown to contribute to mast cell recruitment and tumor angiogenesis in the prostate cancer microenvironment." (PMID 33807058, 2021). "Moreover, PKD2/3 depletion not only reduced SCF, CCL5 and CCL11 expression in prostate cancer cells but also inhibited angiogenic factors in MCs." (PMID 30841931, 2019). "To further clarify whether PKD2/3 mediated chemotactic migration of MCs through upregulation of SCF, CCL5, and CCL11 in prostate cancer, we performed migration assay for P815 MCs in a transwell plate." (PMID 30841931, 2019). "Taken together, these data provide evidence that PKD2 and PKD3 could promote prostate cancer progression through the recruitment of MCs and tumor angiogenesis in prostate cancer microenvironment." (PMID 30841931, 2019). "To examine whether Erk1/2 signaling is required for PKD2/3 induced -SCF, CCL5, and CCL11 expression in tumor cells, we first analyzed the interaction of endogenous PKD2 or PKD3 with Erk1/2 in prostate cancer cells." (PMID 30841931, 2019). "Taken together, these data suggested that PKD2/3-regulated SCF, CCL5 and CCL11 secretion in prostate cancer cells may be the key factors that mediated migration and recruitment of MCs in tumor microenvironment." (PMID 30841931, 2019). "In order to investigate whether PKD2 and PKD3 of prostate cancer cells regulate HUVEC cells tube formation in MCs-dependent manner, we first detected the effect of PKD2 and PKD3 of prostate cancer cells on the angiogenic factors expression in the P815 MCs." (PMID 30841931, 2019).
prostate carcinoma (continued). "In addition, PKD isoforms directly activate the NF-κB pathway: In HeLa cells, PKD1 activates NF-κB via oxidative stress signaling, while PKD2 supports the pIKKβ degradation pathway, and PKD3 is responsible for p65 phosphorylation of NF-κB in prostate cancer cells." (PMID 29258556, 2017). "Yet, a direct PKD3–Hsp90 (and PKD2–Hsp90) interaction was detected by PLA experiments in LNCaP cells, demonstrating that Hsp90 also chaperones PKD3 and PKD2 in non-metastatic prostate cancer cells." (PMID 36672148, 2023). "Co-immunoprecipitation assay showed that endogenous PKD2 or PKD3 interacted with Erk1/2 in DU145 and PC-3 M prostate cancer cells, but not with p38." (PMID 30841931, 2019).
polycystic kidney disease 2 (12 papers, 2013 to 2025). Autosomal dominant polycystic kidney disease caused by a mutation in PKD2. "included one mother with a likely pathogenic variant in PKD2, causative of polycystic kidney disease type 2, and another mother with a likely pathogenic variant in SDHB, causative of pheochromocytoma." (PMID 39960876, 2025). "The majority of ADPKD cases are due to mutations in the genes polycystic kidney disease 1 (PKD1) and polycystic kidney disease 2 (PKD2), which encode for polycystin-1 (PC1) and polycystin-2 (PC2) protein, respectively." (PMID 38474131, 2024).
gout (9 papers, 2018 to 2023). A condition characterized by painful swelling of the joints, which is caused by deposition of urate crystals. "Recent studies suggested that PKD2 is associated with urate and gout, but contrary results were observed in other studies." (PMID 32000861, 2020). "We identified three genes, which were significantly associated with the risk of gout (PKD2, NUTD9, and NAP1L5), with NUTD9, and NAP1L5 reported at the first time." (PMID 30899057, 2019). "Through systematic integration of lymphoblastoid eQTL and SNP associations from our discovery GWAS analysis, PKD2 expression showed the most significant association with gout (LBF = 6.89, Psher = 1.08 × 10−5) followed by NUTD9, NAP1L5, and BRE." (PMID 30899057, 2019). "Sherlcok analysis identified three genes, which were significantly associated with the risk of gout (PKD2, NUTD9, and NAP1L5)." (PMID 30899057, 2019). "In addition, we conducted Sherlock analysis to identify susceptibility genes in with regulatory function in gout, and identify three genes, which were significantly associated with the risk of gout (PKD2, NUTD9, and NAP1L5)." (PMID 30899057, 2019). "Rs2728121 in PKD2 and rs1481012 in ABCG2 affect the etiology of diseases and are associated with elevated serum urate, hyperuricemia, and gout, which was in agreement with our findings that rs1481012 affects gout." (PMID 38060535, 2023). "A study on Chinese patients revealed that the epistatic interactions between PKD2 and ABCG2 affect serum urate concentration and gout risk." (PMID 38060535, 2023). "The interaction between PKD2 SNP rs2725220 and nutritional factors increases the risk of HUA and gout in Koreans." (PMID 35922835, 2022). "PKD2 is located nearby ABCG2, which encodes a urate transporter that plays a certain role in serum urate concentrations and gout risk." (PMID 32000861, 2020). "Our findings indicate epistasis between PKD2 and ABCG2 influence serum urate concentrations, hyperuricemia and gout risk, thus providing insight into the pathogenesis of gout." (PMID 32000861, 2020). "Currently, the biological mechanism on how ABCG2 interacts with PKD2/NAP1L5 in the pathogen of gout is unclear." (PMID 30899057, 2019). "Genome-wide association studies (GWASs) have explored many genes associated with gout, for instance, ABCG2, PKD2, SLC2A9, KCNQ1, SLC22A12 and SLC17A1 for gout disease among individuals of European descent." (PMID 30899057, 2019). "One eSNP (rs4148155) showed significant association with both PKD2 (LBFG = 7.02, PeQTL = 2.00 × 10−5) and NAP1L5 expression (LBF = 5.62, PeQTL = 2.00 × 10−4) and strong evidence for association with gout (PGWAS = 5.49 × 10−18)." (PMID 30899057, 2019). "Even though serval GWAS studies found PKD2 variants associated with serum urate and gout, none variants in the PKD2 gene were independently associated with serum urate and gout conditional on the ABCG2 variants." (PMID 32000861, 2020). "Furthermore, no functional experiments are suggesting the contribution of PKD2 on serum urate and gout to date." (PMID 32000861, 2020). "Through this strategy, our results suggested that epistatic interactions between PDK2 and ABCG2 contributed to serum urate and gout and that PKD2 is supposed to influence the progression from elevated serum urate to hyperuricemia to gout by epistatically interacting with ABCG2." (PMID 32000861, 2020). "Therefore, we performed a systemic analysis to explore the role of PKD2 on the development of hyperuricemia and gout." (PMID 32000861, 2020). "But there are strong clinical and genetic reports linking gout and PKD2." (PMID 30899057, 2019). "This study also explores whether PKD2 genes may interact with rs2231142 genotypes in the development of gout." (PMID 29453348, 2018). "In addition, five genes (PKD2, SLC2A9, SLC17A1, SLC17A4 and SLC17A2) were determined to influence the risk of gout (all PFDR < 0.05)." (PMID 29497127, 2018).